BRAF (B-Raf proto-oncogene, serine/threonine kinase)
Diseases named in the same sentence as BRAF in open-access papers (continued):
Sharing a sentence is not in itself a finding about the gene and the disease.
tumor (continued). "BRAF inhibitors, used as therapy in patients with these mutations, often lead to tumour resistance and, thus, the use of MEK inhibitors was introduced in clinics." (PMID 36726591, 2022). "The TGFβ signaling pathway and tumor suppressor SMAD4 mutations have been implicated in the serrated colon carcinogenesis pathway commonly resulting from BRAF mutations." (PMID 36295658, 2022). "The BRAF V600E mutation is found in up to 80% of benign naevi, suggesting that it also functions as a cancer-initiating mutation." (PMID 35159386, 2022). "Specific mutations in MMs lead to differences in prognosis, therapy administration and response for wild‐type vs. BRAF‐mutated tumours." (PMID 35080260, 2022). "The BRAF expression was significantly associated with tumor type (p=0.008), and the higher expression was associated with 13 (48.15%) PTC cases." (PMID 35646190, 2022). "NTRK gene fusions tend to be the primary oncogenic drivers in tumours that harbour them and co-occurrence with other known oncogenic alterations, including BRAF mutations, is uncommon." (PMID 35333737, 2022). "According to the Catalogue of Somatic Mutations in Cancer, it is estimated that 5–7% of all human neoplasms have BRAF alterations." (PMID 35646190, 2022). "Recent work showed that RNF43 is associated with aggressive tumor biology along with BRAF mutation in right sided CRC18, further supporting a distinct pathogenic mechanism and regional preference for Wnt pathway alterations." (PMID 35907983, 2022). "To further reinforce the association between loss of MITF and resistance to MAPK inhibition, we used tumor data from 21 patients treated with BRAF inhibitors alone where transcriptomic data were obtained on available 50 pre- and postrelapse tumors." (PMID 36040798, 2022). "We found that P. micra and F. nucleatum often colonise the same tumours, and that tumours colonised with P. micra and/or F. nucleatum more often are BRAF-mutated and of the MSI subtype." (PMID 36497419, 2022). "Overall, all 46 patients had BRAF mutation results from ctDNA, and 29 (63%) also had results from tumor tissue samples." (PMID 35159044, 2022). "The gold dashed line represents the patients with KRAS and BRAF wild-type (double wt) tumours and the black dashed/dotted line represents the BRAF-mutated microsatellite instable (MSI (mutBRAF/MSI) tumours." (PMID 34887523, 2022). "Later, establishing a mouse monoclonal antibody (VE-1) allowed for the analysis of IHC for the BRAF V600E mutation in numerous tumours." (PMID 36428683, 2022). "Study results suggested that the OS of patients with BRAF-mutated CRLM was worse in those with positive primary tumor lymph nodes, embryonic antigen (CEA) > 200 mg/L, and concurrent tumor metastasis." (PMID 36077604, 2022). "Having a BRAF-mutation was associated with more patients receiving anti-tumor treatment in the last 3 months." (PMID 35247992, 2022). "To do so, we separated the tumor samples into BRAF mutant, which only contain BRAF V600E mutations, and wild type." (PMID 35044091, 2022). "The study population consisted of patients with advanced cutaneous melanoma with a BRAF-V600 mutated tumor who were treated with first-line BRAF-MEK inhibitors between 2013 and 2017." (PMID 35703270, 2022). "High T‐cell/low B‐cell gene expression signatures in pre‐treatment tumour samples from patients subsequently treated with BRAF and MEK inhibitors were associated with longer survival compared with high T‐cell/high B‐cell signatures." (PMID 35218154, 2022). "The clinical data of PTC patients, including sex, age, radiotherapy history, metastasis stage, lymph node stage, tumor stage and neoplasm disease stage, were compared between the BRAF-mutated and wild-type groups." (PMID 35757399, 2022). "Precision medicine originated in the early 2000s, when advances in genome sequencing made it possible for clinicians and researchers the analysis of the tumor’s DNA to identify driver mutations (e.g., BRAF, HER2)." (PMID 35654785, 2022).
tumor (continued). "For BRAF, more and more co-mutations have been found between BRAF and other genes, which also indicates that the branching cloning process occurs at the early stage of tumor evolution, which leads to the generation of BRAF co-mutations." (PMID 35912223, 2022). "BRAF mutation in PTCs is associated with rapid cell growth, aggressive tumor characteristics, and higher mortality rates." (PMID 36009596, 2022). "Molecular testing showing BRAF V600E mutation on the initial tumor biopsy was obtained; therefore, the surgical option was postponed and therapy with vemurafenib started (750 mg/m2 daily, progressively increased to 1100 mg/m2)." (PMID 36447197, 2022). "Several studies have investigated risk factors of MBM, such as age, race, gender, location of primary tumor, histologic subtype, BRAF mutation status, and tumor stage." (PMID 36551594, 2022). "More generally, oncogenic BRAF mutations have been associated with autophagy-promoted tumorigenesis and tumor progression in other tumor models." (PMID 36009541, 2022). "It is important to note that although BRAF inhibitors show comparative efficacy in both the V600E and V600K mutations, the two tumour types have sometimes been considered as distinct entities." (PMID 35080260, 2022). "More specifically, findings of a heterogeneously distributed BRAF mutation that is confined to a subset of tumor cells in small-size tumors suggest that monoclonality for BRAF predominating in more-advanced stages of PTC is the result of tumor evolution." (PMID 34379110, 2022). "Identification of the specific subtype of Irish CRC patients likely to develop a BRAF mutation was a fundamental finding of this report, this being females over the age of 50 presenting with right-sided tumours." (PMID 34877621, 2022). "The MMR status was known for 40 tumors, of which 34 (85%) were MMR-proficient and 6 (15%) were MMR-deficient with MLH1/PMS2 loss of staining and positive BRAF mutation, which associates with a sporadic tumor." (PMID 36203446, 2022). "The first finding of this work is that tumor samples carrying BRAF-mutations over-express NAMPT, as demonstrated by analyzing the TCGA dataset, and MM and THC tissue microarrays." (PMID 35272691, 2022). "As a third case report, we present patient CRC-0042 (stage II) who had the following mutations detectable by sequencing of the original tumor: BRAF (N581I at 28.7% VAF), NRAS (G12V at 41.9%), and PIK3CA (E545K at 57.7%)." (PMID 36579573, 2022). "BRAF mutation studies were carried out via real-time PCR of tumor specimens, as well as BRAFV600E-specific staining of tumors." (PMID 35798969, 2022). "DNA– and/or RNA–based NGS panels can be used either upfront or to confirm the presence of NTRK fusion in TRK immunopositive tumours or those devoid of other driver mutations, such as those in BRAF and RAS genes." (PMID 35237889, 2022). "The results of previous studies on the association between the BRAF V600E mutation and tumor size are contradictory; however, this can also be attributed to different statistical methods and the interpretations of the results." (PMID 36672561, 2022). "On the tumour stage, BRAF mutation was reported highest in the “late stage” at 59.9% (95% CI: 48.2–70.7), while on location, “colon” recorded the highest BRAF mutation of 67.9% (95% CI: 37.3–42.5)." (PMID 35782059, 2022). "F. nucleatum abundance has also been associated with tumour location (increased in proximal versus distal cancers), BRAF mutation, high grade histology and microsatellite instability (MSI)." (PMID 34995318, 2022). "BRAF V600E mutation alone was strongly associated with male sex, smaller tumor size, classic PTCs, less perinodal infiltrations, and N1, M0 stages of PTCs." (PMID 36230856, 2022). "As comprehensive genomic profiling of patients’ tumor samples is increasingly being used in clinical routine, it is likely that more uncharacterized BRAF gene mutations will be detected in the future." (PMID 35869122, 2022).
tumor (continued). "Although dMMR patients usually have better prognosis, those whose tumours contain BRAF mutations have shown worse prognosis in metastatic CRC." (PMID 36134447, 2022). "There are two subclasses of CIMP tumours: CIMP-high tumours (or CIMP1) have BRAF mutations and are microsatellite-unstable; CIMP-low (or CIMP2) tumours have KRAS mutations." (PMID 35055034, 2022). "Among them, 549 (75.0%) had the BRAF V600E mutation in both lesions, 101 (13.1%) had it in the main tumor alone, and 40 (5.5%) in the contralateral tumor alone." (PMID 36230856, 2022). "In our cohort, BRAF was associated with younger age and tumor location in the trunk in this cohort, which are similar findings to what have been reported in the general population." (PMID 35712493, 2022). "High levels of P. micra in tumour tissue were significantly associated with age and female gender, as well as BRAF-mutated tumours and tumours of the MSI subtype." (PMID 36497419, 2022). "Drug therapy is known to exert selective pressure additionally promoting for e.g., oncogenic RAS or BRAF variants and thus contribute to the active selection for therapy-resistant tumor stem cells." (PMID 35448502, 2022). "Further analysis of the BRAF mutations and the relationship with tumor stromal biomarkers would indeed be valuable." (PMID 36242015, 2022). "The clinical and pathological features of 102 patients who had IHC detection of BRAFV600E mutation were also compared between two groups [tumor with BRAF (+) vs. BRAF (−)]." (PMID 36307486, 2022). "High DDR1 immunostaining score was significantly associated, on univariate analysis, with male sex, left tumor location, BRAF wild type status, KRAS mutated status, and Annexin A10 negativity." (PMID 35205677, 2022). "The identification of the BRAFV595E mutation in canine TCC and its high prevalence pointed to the possibility of targeting the BRAF/MAPK pathway via a therapeutic approach in those tumours carrying the mutation." (PMID 35324835, 2022). "In these three patients, BRAF mutation status analysis in tumor tissue was performed using the Cobas 4800 BRAF V600 Mutation Test." (PMID 35159044, 2022). "Activating mutations of the proto-oncogene BRAF (mutBRAF/wtNRAS, ∼60% of patients) lead to uncontrolled tumor growth." (PMID 35214043, 2022). "BRAF V600E test results were recorded for all patients with tumour MLH1 loss at two hospitals (H1, H7), of which one (H7) further included MLH1 promoter hypermethylation test results where no somatic BRAF V600E variant was found." (PMID 35509103, 2022). "Type I tumours are low-grade, more indolent, and less aggressive tumours that are characterized by mutations in mitogen-activated protein kinase (MAPK) regulator pathways (e.g. KRAS or BRAF)." (PMID 35545786, 2022). "Treatment of BRAF-mutated cell lines with two different NAMPTi was followed by significant reduction of tumor growth, indicating NAMPT addiction in these cells." (PMID 35272691, 2022). "The first widely used BRAF‐mutant inhibitor is known as vemurafenib and it initially demonstrated promising results, reducing the risk of death and tumour progression by 63% and 74% respectively." (PMID 35040264, 2022). "A binary logistic regression model was established to evaluate the effects of CNV, BRAF mutation, and tumor size on LN metastasis in patients with PTC." (PMID 36313748, 2022). "Actionable biomarkers such as RAS and BRAF mutations, microsatellite instability/mismatch repair status, and tumor mutational burden have been incorporated into national and societal guidelines." (PMID 36230522, 2022). "Among them, BRAF presents the most remarkable reactivity of the others and can be activated by mutation in tumor cells." (PMID 35799213, 2022). "It has been indicated that the hindrance of A2AR signaling can restrain lung metastasis through improved immune cell infiltration, particularly CD8+ T cells into the tumor microenvironment in an SM1WT1 BRAF-mutated melanoma tumor model." (PMID 32902664, 2021).
tumor (continued). "Mutational signatures, tumor mutational burden (TMB), tumor indel burden, and variants in cancer driver genes (BRAF, KRAS, POLE, POLD1 and DNA mismatch repair (MMR) genes) were analyzed for available samples." (PMID 33672345, 2021). "The combined treatment of oHSV and MEKi performed in this study indicated that combination of MEKi and oHSV increased tumor cell killing by facilitating viral replication, only for BRAF V600E-mutated tumor cells." (PMID 34578339, 2021). "This study demonstrated that triplets of vemurafenib, irinotecan, and cetuximab were well tolerated and exceeded tumour regression in refractory BRAF-mutated mCRC." (PMID 34663410, 2021). "Although genes such as BRAF carry one hotspot responsible for almost all mutations observed in the gene in tumor cohorts, many genes implicated in tumor progression and proliferation have a widely distributed pattern of genomic alterations." (PMID 33957863, 2021). "The CTNNB1S45F mutation was detected in four patients (#6, #9, #10, and #12; 28%, all BRAF positive) with a 32.2%, 2.1%, 0.4%, and 0.7% alternative allele frequency in their tumor samples, respectively." (PMID 34356096, 2021). "Liquid biopsy provides a minimally invasive platform for the detection of tumor-derived information, including hotspot mutations, such as BRAF V600E." (PMID 33799709, 2021). "We conducted a prospective study to investigate the relationship between the perioperative mutant allele frequency (MAF) of BRAF V600E and tumor recurrence, and to evaluate the possibility of early detection of recurrence." (PMID 34168268, 2021). "Approximately 90% of activating BRAF mutations present in neoplasms are the result of substitution of a valine to glutamic acid at position 600: BRAF p.V600E." (PMID 33795686, 2021). "In the field of precision thyroid oncology, the BRAF oncogene is frequently mutated in TC (25-80%), promoting aggressive tumor growth." (PMID 33391536, 2021). "The discovery of oncogenic BRAF V600E mutation in LCH has provided additional evidence that LCH is a neoplasm." (PMID 34307217, 2021). "This broad application of 1B3 in different oncogene-driven tumors is supported by the 50% tumor growth inhibition of BRAF-mutated A2058-derived tumors after INT-1B3 treatment in vivo." (PMID 33747358, 2021). "Bei Vorliegen einer BRAF-Mutation in einem dMMR/MSI-H-Tumor kann ein Lynch-Syndrom weitestgehend ausgeschlossen werden." (PMID 33956173, 2021). "If the tumor has BRAF V600-activating mutation, BRAF inhibitor combined with MEK inhibitor is preferred (e.g., dabrafenib/trametinib, vemuragfenib/cobimetinib, and encorafenib/binimetinib; category 1, high-level evidence)." (PMID 34065883, 2021). "Preoperative administration of BRAF inhibitors is expected to shrink the tumor and prevent surgery-associated complications." (PMID 34966836, 2021). "Among patients receiving anti-EGFR-based therapies, 23 (34%) had a RAS and BRAF wild-type tumour, while a RAS or BRAF mutation was found in 16 (23%) and 6 (9%) cases, respectively." (PMID 33024268, 2021). "Grb2-associated binders 2 (GAB2) contributed to tumor growth and angiogenesis through the upregulation of vascular endothelial growth factor expression, and it was also important in BRAF inhibition resistance." (PMID 34208938, 2021). "Expansion and persistence of CD4+ T cells directed against another tumor-specific mutation (BRAF) has also been observed in another patient who achieved long-term tumor control after TIL transfer." (PMID 33546283, 2021). "High VISTA expression correlated with better disease-free survival (DFS), high tumor infiltrative lymphocyte, microsatellite instability, BRAF mutational status as well as lower tumor stage." (PMID 34465822, 2021).
tumor (continued). "They show that this approach generates target engagement, T-cell activation, tunable in vivo half-life extension, cellular cytotoxicity dependent on the cell surface levels of EGFR and can inhibit growth of BRAF mutated EGFR-positive tumours in mice." (PMID 33686177, 2021). "KRAS, NRAS, and BRAF mutations in PDTOs were matched to 86.6%, 100%, and 100% of those in corresponding tumor tissues, respectively." (PMID 34359661, 2021). "The tall cell variant is the most aggressive tumor, indicating that BRAF mutations are associated with poorer outcomes." (PMID 34345541, 2021). "Among tumor tissue KRAS/BRAF mutation carriers, tumor‐derived cfDNA was detected by droplet digital polymerase chain reaction (ddPCR) in plasma of 93% of CRC‐LM and 20% of CRC‐PM patients and in peritoneal fluid in all CRC‐PM patients." (PMID 33635598, 2021). "This particular enteroid was generated from a sessile serrated tumor, and BRAF mutations are known to be drivers for this tumor type." (PMID 34138755, 2021). "Liquid biopsies of circulating tumour DNA in the plasma, serum and CSF isolated from 29 CNS paediatric patients revealed the presence of the BRAF V600E mutation." (PMID 33557011, 2021). "The whole distribution of different molecular characteristics, such as TNM stage, BRAF, tumor mutation burden (TMB), and survival status (DFS and OS) in PTC samples between clusters, was significantly different." (PMID 34628367, 2021). "The consideration of using targeted biological agents in tumours that lack RAS/BRAF mutations in left-sided CRC." (PMID 34440099, 2021). "Generally, BRAF mutations are considered early oncogenic events and are therefore present in most tumor cells, resulting in a low intratumoral heterogeneity." (PMID 34768746, 2021). "Subdivided by size of tumour, the BRAF V600E mutation was detected in 43.6% of PTMCs and 42.4% of small PTCs." (PMID 34742355, 2021). "Dutch CRC guidelines recommend, in line with the European guidelines, to determine both mismatch repair status in stage II-IV tumors, and RAS and BRAF mutation status in tumor of patients with metastatic CRC prior to the start of systemic treatment." (PMID 33594104, 2021). "The BRAF V600E mutation was associated with aggressive tumour features in both PTMC (p = 0.011) and small PTC (p < 0.001)." (PMID 34742355, 2021). "The primary tumor of 90 patients harbored a BRAF mutation (56.6%), which was V600E in 87%, V600K in 10%, and V600R in 3% of the patients." (PMID 34209415, 2021). "NF-κBp 65, NF-κBp50, VEGF, HIF-2; VHL elevated mRNA level by 10.6; 13.5; 240.6; 11.5; 368.5 times found in tumors with mutation, respectively, compared to the primary tumor with the wild variant of the BRAF gene." (PMID 34319022, 2021). "BRAF inhibitors (Dabrafenib and Vemurafenib), however, show higher overall survival and tumour response in BRAF V600E mutated pLGGs than conventional therapies in some studies." (PMID 33557011, 2021). "PLX51107, a next-generation BETi, impaired tumor growth to differing degrees in BRAF V600E syngeneic mouse models, effects that were linked to the influx of TAMs." (PMID 34575678, 2021). "In this study, we compared the association between the clinicopathological characteristics (including age, gender, tumor size, BRAF V600E mutation status and the histological types) among the different TBSRTC categories." (PMID 34664843, 2021). "TERT promoter mutations promote telomerase activation; in addition, a synergistic effect with driver mutations, mainly BRAF, in promoting tumor aggressiveness has been demonstrated." (PMID 33799953, 2021). "EOC is further classified into Type I and Type II tumours Low-grade tumours are type I tumours and carry mutations of BRAF, KRAS, and PTEN." (PMID 34987905, 2021). "Detection of BRAF mutation in cell free tumor DNA has prognostic value for survival and its dynamics has an excellent correlation with clinical response, but not with progression." (PMID 34853302, 2021).